C19orf47 (chromosome 19 open reading frame 47)
Synonyms: FLJ36888
Tractability: PROTAC: UniProt records ubiquitination sites on it; ubiquitination databases record sites on it; its protein half-life has been measured.
Gene: Protein-coding gene on chromosome 19 (40,319,536 to 40,348,527, reverse strand). Ensembl gene ENSG00000160392.
Subcellular location (Human Protein Atlas): Nucleoplasm; Nuclear speckles
Gene Ontology:
Molecular function: protein binding
Cellular component: nucleus
Genetic constraint (gnomAD): Loss-of-function variants: 18 observed, 30.74 expected, observed/expected ratio (o/e) 0.59, 90% interval 0.4 to 0.87. The upper end of that interval is the gene's LOEUF score, 0.87, which puts it in group 3 of 6, group 1 being the genes least tolerant of losing a copy. Missense variants: 484 observed, 530.86 expected, observed/expected ratio (o/e) 0.91, 90% interval 0.85 to 0.98. Synonymous variants: 202 observed, 211.36 expected, observed/expected ratio (o/e) 0.96, 90% interval 0.85 to 1.07.
Homologues: Orthologues: macaque C19H19orf47 (99% identical), chimpanzee C19H19orf47 (98% identical), dog C19orf47 (96% identical), pig C19orf47 (93% identical), rabbit C19orf47 (91% identical), mouse 2310022A10Rik (90% identical), rat C1h19orf47 (90% identical), guinea pig C19orf47 (83% identical), tropical clawed frog c8h19orf47 (61% identical), zebrafish C18H19orf47 (54% identical), Drosophila melanogaster CG16812 (29% identical), Caenorhabditis elegans F53F8.5 (23% identical).